CDK2 (cyclin dependent kinase 2)
Description:
Serine/threonine-protein kinase involved in the control of the cell cycle; essential for meiosis, but dispensable for mitosis. Triggers duplication of centrosomes and DNA. Acts at the G1-S transition to promote the E2F transcriptional program and the initiation of DNA synthesis, and modulates G2 progression; controls the timing of entry into mitosis/meiosis by controlling the subsequent activation of cyclin B/CDK1 by phosphorylation, and coordinates the activation of cyclin B/CDK1 at the centrosome and in the nucleus. Crucial role in orchestrating a fine balance between cellular proliferation, cell death, and DNA repair in embryonic stem cells (ESCs). Activated by the CDK-activating kinase (CAK) complex consisting of CDK7, cyclin-H/CCNH and MAT1, which is a master regulator of CDK activity. Activity of CDK2 is maximal during S phase and G2; activated by interaction with cyclin E during the early stages of DNA synthesis to permit G1-S transition, and subsequently activated by cyclin A2 (cyclin A1 in germ cells) during the late stages of DNA replication to drive the transition from S phase to mitosis, the G2 phase. EZH2 phosphorylation promotes H3K27me3 maintenance and epigenetic gene silencing. Cyclin E/CDK2 prevents oxidative stress-mediated Ras-induced senescence by phosphorylating MYC. Involved in G1-S phase DNA damage checkpoint that prevents cells with damaged DNA from initiating mitosis; regulates homologous recombination-dependent repair by phosphorylating BRCA2, this phosphorylation is low in S phase when recombination is active, but increases as cells progress towards mitosis. In response to DNA damage, double-strand break repair by homologous recombination a reduction of CDK2-mediated BRCA2 phosphorylation. Involved in regulation of telomere repair by mediating phosphorylation of NBN. Phosphorylation of RB1 disturbs its interaction with E2F1. NPM1 phosphorylation by cyclin E/CDK2 promotes its dissociates from unduplicated centrosomes, thus initiating centrosome duplication. Cyclin E/CDK2-mediated phosphorylation of NPAT at G1-S transition and until prophase stimulates the NPAT-mediated activation of histone gene transcription during S phase. Required for vitamin D-mediated growth inhibition by being itself inactivated. Involved in the nitric oxide- (NO) mediated signaling in a nitrosylation/activation-dependent manner. USP37 is activated by phosphorylation and thus triggers G1-S transition. CTNNB1 phosphorylation regulates insulin internalization. Phosphorylates FOXP3 and negatively regulates its transcriptional activity and protein stability (By similarity). Phosphorylates ERCC6 which is essential for its chromatin remodeling activity at DNA double-strand breaks. Acts as a regulator of the phosphatidylinositol 3-kinase/protein kinase B signal transduction by mediating phosphorylation of the C-terminus of protein kinase B (PKB/AKT1 and PKB/AKT2), promoting its activation.
Synonyms: CDKN2; p33(CDK2)
Tractability: Small molecule: a drug acting on it is in phase 2 or 3 trials; a structure with a bound ligand is known; a high-quality ligand is known; it has a high-quality binding pocket; it belongs to a druggable protein family. PROTAC: it is named in the literature on targeted protein degradation; ubiquitination databases record sites on it; a small molecule that binds it is known.
Target class: CMGC protein kinase CDC2 subfamily; Kinase; CMGC protein kinase CDK family; CMGC protein kinase group; Enzyme; Protein Kinase
Chemical probes: BMS-265246, CPS2, INX-315 (high quality), PD004830, PD005030, PD008140, PD080935, PD080983, PD081065, PD081370, PD081460, PD081500, PD081582, PD081953, PD081965, PD082361, PD082409, PD082520, PD083131, PD083191, and 14 more
Safety:
Unwanted effects reported when the protein is acted on. In parentheses: how it was acted on, where the effect was seen, and who reports it.
cardiomyocyte hyperproliferation (activation; cardiovascular system; source: Urban et al. (2012))
heart disease (cardiovascular system; source: Force et al. (2011))
Gene: Protein-coding gene on chromosome 12 (55,966,781 to 55,972,789, forward strand). Ensembl gene ENSG00000123374.
Subcellular location: Cytoplasm, cytoskeleton, microtubule organizing center, centrosome; Nucleus, Cajal body; Cytoplasm; Endosome
Subcellular location (Human Protein Atlas): Nucleoplasm; Basal body; Calyx; Centrosome; Plasma membrane
Pathways (Reactome):
Cell Cycle: Activation of ATR in response to replication stress; Cyclin A/B1/B2 associated events during G2/M transition; Cyclin A:Cdk2-associated events at S phase entry; Cyclin D associated events in G1; Cyclin E associated events during G1/S transition; G0 and Early G1; G2 Phase; Phosphorylation of proteins involved in G1/S transition by active Cyclin E:Cdk2 complexes; Regulation of APC/C activators between G1/S and early anaphase; SCF(Skp2)-mediated degradation of p27/p21; Telomere Extension By Telomerase
DNA Replication: Activation of the pre-replicative complex; CDK-mediated phosphorylation and removal of Cdc6; Orc1 removal from chromatin
Cellular responses to stimuli: DNA Damage/Telomere Stress Induced Senescence; Senescence-Associated Secretory Phenotype (SASP)
Developmental Biology: Regulation of MITF-M-dependent genes involved in cell cycle and proliferation; Transcriptional regulation of granulopoiesis
DNA Repair: Processing of DNA double-strand break ends
Disease: Defective binding of RB1 mutants to E2F1,(E2F2, E2F3)
Hemostasis: Factors involved in megakaryocyte development and platelet production
Reproduction: Meiotic recombination
Signal Transduction: PTK6 Regulates Cell Cycle
Gene Ontology:
Molecular function: cyclin binding; cyclin-dependent protein kinase activity; cyclin-dependent protein serine/threonine kinase activity; histone kinase activity; protein binding; protein domain specific binding; protein serine kinase activity; protein serine/threonine kinase activity; ATP binding; kinase activity; magnesium ion binding; protein kinase activity
Biological process: centriole replication; negative regulation of protein localization to chromatin; peptidyl-serine phosphorylation; positive regulation of cell population proliferation; positive regulation of heterochromatin formation; post-translational protein modification; protein phosphorylation; Ras protein signal transduction; regulation of heterochromatin organization; telomere maintenance in response to DNA damage; cellular response to nitric oxide; cellular senescence; centrosome duplication; DNA replication; G1/S transition of mitotic cell cycle; G2/M transition of mitotic cell cycle; meiotic cell cycle; mitotic G1 DNA damage checkpoint signaling; positive regulation of DNA replication; regulation of anaphase-promoting complex-dependent catabolic process; regulation of mitotic cell cycle; chromatin remodeling
Cellular component: Cajal body; centrosome; ciliary basal body; cyclin A2-CDK2 complex; cyclin E1-CDK2 complex; cyclin E2-CDK2 complex; cyclin-dependent protein kinase holoenzyme complex; cytoplasm; endosome; nucleoplasm; nucleus; cyclin A1-CDK2 complex; cytosol; chromosome, telomeric region; condensed chromosome; nuclear envelope; transcription regulator complex; X chromosome; Y chromosome
Genetic constraint (gnomAD): Loss-of-function variants: 5 observed, 26.94 expected, observed/expected ratio (o/e) 0.19, 90% interval 0.096 to 0.39. The upper end of that interval is the gene's LOEUF score, 0.39, which puts it in group 1 of 6, group 1 being the genes least tolerant of losing a copy. Missense variants: 187 observed, 333.31 expected, observed/expected ratio (o/e) 0.56, 90% interval 0.5 to 0.63. Synonymous variants: 116 observed, 127.99 expected, observed/expected ratio (o/e) 0.91, 90% interval 0.78 to 1.06.
Homologues: Orthologues: chimpanzee CDK2 (100% identical), dog CDK2 (99% identical), mouse Cdk2 (99% identical), rabbit CDK2 (99% identical), rat Cdk2 (99% identical), pig CDK2 (99% identical), guinea pig CDK2 (98% identical), zebrafish cdk2 (90% identical), tropical clawed frog cdk2 (87% identical). Paralogues in human: CDK3 (76% identical), CDK1 (65% identical), CDK5 (58% identical), CDK16 (53% identical), CDK18 (53% identical), CDK17 (53% identical), CDK14 (50% identical), CDK6 (48% identical), CDK11B (46% identical), CDK11A (46% identical), CDK15 (46% identical), CDK13 (46% identical), and 14 more.
Diseases named in the same sentence as CDK2 in open-access papers:
CDK2 is named in the same sentence as 246 diseases in open-access papers, as found by Europe PMC text mining. Sharing a sentence is not in itself a finding about the gene and the disease. The quoted sentences say what the papers report.
breast cancer (261 papers, 2002 to 2026). A primary or metastatic malignant neoplasm involving the breast. "Preclinical studies revealed that CDK2-deficient mice are resistant to cyclin E-mediated mammary tumours, suggesting a role for CDK2 in early BC pathogenesis." (PMID 38732271, 2024). "Studies available in the scientific literature indicate that ATRA targets CDK2, causing an arrest of breast cancer cell proliferation." (PMID 39323992, 2024). "While CDK2 hyperactivation is linked to basal-like breast cancer tumors, aberrant expression of CDK4 is linked to drug resistance." (PMID 37596623, 2023). "For the early G1-to-S-phase cell cycle genes, CDK6 and CCNE1 both showed a strong association with TNBC and basal-like breast cancers in all three cohorts, while CDK2, CDK4 and CCND1 expression were high across all patient samples." (PMID 35884422, 2022). "Compounds II showed a potent CDK2 inhibitory activity with IC50 of 52.75 nM inducing cell cycle arrest of MCF-7 breast cancer cells wihin the G2/M phase causing cell apoptosis." (PMID 35470754, 2022). "Copy number alteration of CDK2 is associated with dysfunctional T-cell phenotype, high death risk, and shorter survival of lymphoma, leukemia, and breast cancer patients while CDK4 predicted a worse prognosis of the brain, lymphoma, and breast cancer patients." (PMID 33668805, 2021). "Nevertheless, a novel potent and selective CDK2/4/6 inhibitor, PF-06873600, was recently developed and demonstrated activity in Rb-deficient palbociclib-resistant breast cancer cell models exhibiting high cyclin E expression." (PMID 34771560, 2021). "There is evidence that Her2+ breast cancer (BC) cell lines resistant to trastuzumab show amplification and overexpression of cyclin E. These lines are more sensitive to inhibition of CDK2/9 by fadraciclib, which caused both cell cycle arrest and apoptosis." (PMID 32645016, 2020). "As CDK2 is associated with multiple cancers, like breast cancer, colorectal cancer, non-small cell lung cancer (NSCLC), hence, circ-Foxo3 also carry out functions in cancers above by forming circ-Foxo3-p21-CDK2 ternary complex." (PMID 28969093, 2017). "To understand the biological roles of LMW-E, we previously generated transgenic mouse models of mammary tumors driven by LMW-E in a setting of CDK2 proficiency or deficiency." (PMID 28107181, 2017). "A decline in Cdk2 activity by ORG-31710 associated with increased p21cip1 was also reported in T-47D breast cancer cells." (PMID 25252652, 2015). "Expression abnormalities in cyclin E and CDK2 are closely associated with the occurrence and development of breast cancer, stomach cancer, colon cancer and other types of tumor." (PMID 25891642, 2015). "CDK1 is known to have a diagnostic value in esophageal and breast cancers, while the expression of CDK2 or its activity seems to have been utilized towards the prognosis of breast, ovarian and oral cancers." (PMID 25349887, 2014). "As such, we designed our electrospun scaffolds to deliver plasmid DNA encoding for shRNA targeting Cdk2, a cell cycle specific protein, coupled to a cellular based assay, i.e. proliferation and cell death, using the human breast cancer cell line, MCF-7." (PMID 23285007, 2012). "The expression of RB/E2F target genes, which is tightly controlled by CDK2 activity, is often deregulated and associated with worse prognosis for tamoxifen-treated breast cancer patients." (PMID 21834972, 2011). "Deregulation of cyclin E/CDK2, an early and frequent finding in breast cancer, has recently been shown to cause an aberrant recruitment of the centrosomal protein kinase PLK4 to centrioles thereby promoting centriole and centrosome overduplication." (PMID 20565777, 2010).
breast cancer (continued). "Furthermore, CDK2 activity has also been implicated in partial resistance to HER2-targeted therapies in breast cancer." (PMID 40949156, 2025). "Preclinically, CDK2-deficient mice were shown to be resistant to cyclin E-mediated mammary tumours." (PMID 38732271, 2024). "It is therefore tempting to speculate that sustained ERK5 signaling neutralizes the antiproliferative effect of anti-HER2 agents in resistant breast cancer cells by promoting RB phosphorylation through the cyclin E–associated CDK2 complex." (PMID 36466034, 2022). "In addition, CDK2 and CDK4 are hypomethylated but are less frequently mutated: CDK2 (2 cases 0.19%) and CDK2 (1 case 0.10%) in breast cancer." (PMID 34421361, 2021). "Altogether, these findings support further clinical evaluation of CDK2 inhibitors like Dinaciclib administered in combination with endocrine therapy as a potentially new treatment strategy against ESR1 mutation expressing breast cancers." (PMID 29137354, 2017). "The present study successfully demonstrated the effective silencing of Cdk2 mRNA and subsequent suppression of breast cancer cell proliferation with an increase in cell death via the use of an electrospun scaffold containing plasmid DNA encoding for shRNA targeting Cdk2." (PMID 23285007, 2012). "In this study, we aimed to identify and design an in-silico promising multitarget drug for breast cancer by simultaneously targeting three critical proteins: Glucocorticoid Receptor, Estrogen Receptor-alpha (ER-alpha), and Cyclin-Dependent Kinase 2 (CDK2)." (PMID 41871133, 2026). "Ongoing clinical trials are currently assessing novel combinations such as PF-07104091 (CDK2-selective inhibitor) with PF-07220060 (CDK4-selective inhibitor) plus ET in advanced HR+/HER2− breast cancer (NCT05262400)." (PMID 40243688, 2025). "In inflammatory breast cancer, CDK2 is critical for the maintenance and expansion of the breast cancer stem cell (BCSC) population." (PMID 40949156, 2025). "The CDK2 inhibitor PF-07104091 is currently being evaluated in two clinical trials involving breast cancer patients." (PMID 40949156, 2025). "In silico analyses likely indicate quercetin as a CDK2 inhibitor in ER+ breast cancer and that quercetin can re-sensitize breast cancer cells to palbociclib by governing the circHIAT1/miR-19a-3p/CADM2 axis." (PMID 40244377, 2025). "HBV infection lead to increased expression levels of several key genes in breast cancer cell lines, including CDK2, PCNA, CCNE2, CXCL8, E2F1, and CASP3." (PMID 40697521, 2025). "In canonical cell cycle machinery, cyclin D1/CDK4 initiates RB phosphorylation and activates CDK2, as observed in ER+ breast cancer models." (PMID 39924553, 2025). "The co-expression of these genes occurs in breast cancer patients highlighting their clinical significance as predictive biomarkers for CDK2-targeted therapies." (PMID 39924553, 2025). "CDK2 was subsequently identified as an important vulnerability in PDOs derived from a canine mammary tumor patient, which can be targeted by an existing inhibitor, PF3600." (PMID 40005944, 2025). "CDK2, PCNA, CXCL8, and E2F1 were involved in the cell cycle, and were associated with worse survival for breast cancer." (PMID 40697521, 2025). "The current study investigated the safety, tolerability, pharmacokinetics, pharmacodynamics, and efficacy of the novel first-in-class CDK2/4/6i PF-06873600 in patients with advanced breast cancer." (PMID 40243688, 2025). "A comparison of essential genes for tumor cells survival identified CDK2 as a functional vulnerability in canine mammary tumors (CMTs) that can be targeted with the PF3600 inhibitor." (PMID 40005944, 2025).